INS (insulin)
Diseases named in the same sentence as INS in open-access papers (continued):
Sharing a sentence is not in itself a finding about the gene and the disease.
Obesity (continued). "Also, it was demonstrated that MOE improved obesity and insulin sensitivity in HFD-fed obese C57BL/6J Mice." (PMID 40255947, 2024). "In addition to their traditional antioxidant and antibacterial activities, phenolic compounds have also been found to regulate α-amylase activity, improve insulin resistance, enhance gut microbiota, and resist obesity." (PMID 39149547, 2024). "Additionally, changing the composition of the intestinal microbiota, avoiding diet‐induced obesity, enhancing insulin sensitivity, and lowering inflammation raise the quantity of Lactobacillus and Bifidobacterium in the gut considerably." (PMID 39619999, 2024). "The objective of this project was to evaluate the impact of two purified sweet-tasting components of stevia, rebaudioside A and D (RebA and RebD), on the development of obesity, insulin resistance, hepatic health, bile acid profile, and gut microbiota in a mouse model of diet-induced obesity." (PMID 38321177, 2024). "The impairment of insulin’s ability to suppress the production of inflammatory and catabolic mediators responsible for OA would be diminished with the onset of IR in individuals with obesity." (PMID 38468219, 2024). "In terms of mechanism, a high level of insulin is required for the development of severe obesity." (PMID 39873003, 2024). "However, under conditions of obesity, these transcription factors, PPARγ and C/EBPα, not only enhance insulin-mediated glucose uptake but also contribute to increased FFA production." (PMID 39683533, 2024). "Fourth, the superior performance of TyG‐BMI might be explained by the effects of blood glucose, lipid metabolism, and obesity on insulin sensitivity." (PMID 39364793, 2024). "Thus, the study group was composed of young patients with an average BMI corresponding to the second degree of obesity, good control of blood pressure and lipid parameters, as well as insulin resistance." (PMID 39064191, 2024). "A potential explanation might be in the different central actions of insulin and possibly leptin in patients with obesity." (PMID 39000449, 2024). "In addition, studies in polycystic ovary syndrome (PCOS) have revealed the impact of obesity and insulin sensitivity on patients, and these factors have also been associated with physical activity in previous studies." (PMID 38783362, 2024). "As previously reported, HFD exposure for 10 months in this mouse cohort resulted in the establishment of a T2D phenotype with obesity over 25% BW increase, fasting hyperglycemia (fasting glucose over 7 mmol/L) and insulin resistance, when compared with SD feeding." (PMID 38864508, 2024). "Insulin can attenuate plasma BCAA levels in healthy, insulin-sensitive individuals with obesity." (PMID 39062958, 2024). "Therefore, by manipulating insulin and its signaling pathways, OS can contribute to excessive fat storage in cells, leading to obesity." (PMID 39000383, 2024). "Our aim was to investigate whether sex-specific differences in the insulin-sensitizing effects of RSG exist on WAT during obesity and inflammation." (PMID 39339665, 2024). "Glucagon-like peptide-1 (GLP-1) receptor agonists, such as liraglutide and semaglutide, have proven effective in resisting obesity and improving hyperglycemia, insulin sensitivity, and blood pressure by inhibiting food intake, as demonstrated in both preclinical and clinical studies." (PMID 39351529, 2024). "Significant advances in DNA microarray technology should promote our understanding of anthocyanin-mediated influence on gene expression and regulatory mechanisms of genes responsible for the prevention of obesity and amelioration of insulin sensitivity through modulation of adipocyte function." (PMID 38254596, 2024). "For example, cyclic mechanical stretch loading reflective of dynamic exercise may provide a tool to improve insulin sensitivity in patients with obesity and T2D." (PMID 39768098, 2024).
Obesity (continued). "Research by Abhishek K using a hepatocyte-specific ANGPTL4 mutant mouse model demonstrated that suppressing ANGPTL4 could prevent diet-induced obesity, reduce ectopic lipid accumulation, and enhance insulin sensitivity and glucose tolerance." (PMID 39176085, 2024). "Consequently, the development of obesity leads to insulin resistance, which necessitates greater amounts of insulin." (PMID 38092958, 2024). "According to a former study, there is an increased risk of cardiovascular diseases i.e. dyslipidemia, obesity, hypertension, and increased resistance to insulin in women with preeclampsia in comparison to those without any pregnancy-related complications." (PMID 39416618, 2024). "Additionally, miR-132 has been found to modulate glucose-stimulated insulin secretion and improve beta cell function in obesity models." (PMID 39195481, 2024). "Here, we observed the Th2 cells-transferred CD3ε−/− mice exhibited reduced fat accumulation accompanied by improvement of insulin sensitivity and glucose tolerance compared with CD3ε−/− counterparts, indicating that Th2 cells limit the pathogenesis and progression of obesity." (PMID 38195424, 2024). "At the same time, physical activity may delay puberty by reducing the synthesis of sex hormones by reducing obesity, or by decreasing insulin levels, increasing sex hormone-binding globulin levels, and decreasing estradiol bioavailability." (PMID 38719835, 2024). "Thus, alterations in MCU function can impair mitochondrial oxidative metabolism, lipid metabolism, and insulin secretion, which are prominent features of obesity." (PMID 38674446, 2024). "One of these recent studies in which BAIBA is related to lower postprandial glucose concentrations in adults with obesity, suggests that adiponectin would modulate this effect by favoring the expression of the insulin gene or the exocytosis of insulin granules." (PMID 38731880, 2024). "Four studies conducted in people with overweight/obesity reported changes in fasting insulin and the pooled analysis showed that a plant-based diet significantly reduced fasting insulin compared with control diets (−4.13 μU/mL, 95% CI (−7.22, −1.04), n = 638, p = 0.009, I2 = 37%)." (PMID 38999858, 2024). "In conditions of obesity or excess energy reserves, insulin resistance may help modulate energy management and protect against disruptions to homeostasis, thereby reducing mortality risk." (PMID 39872311, 2024). "In this study we performed a comprehensive in-vivo screen covering the secretome and receptome to identify hormonal mechanisms and pathways modulating sugar tolerance and cellular responses to insulin in a sugar-induced metabolic state characterized by obesity and resistance to insulin." (PMID 39033139, 2024). "L. plantarum H-87 could inhibit liver fat deposition, insulin resistance, and lipid digestion by changing bile acid enterohepatic circulation and eventually alleviate high-fat-diet-induced obesity." (PMID 39758313, 2024). "Beyond the direct impacts of insulin, obesity may contribute to the activation of alternative pathways, potentially leading to malignant progression." (PMID 38254789, 2024). "Previous research has revealed the inadequate use of growth recovery methods may convert the saving environment into one that promotes insulin resistance, potentially resulting in long-term obesity development." (PMID 39767952, 2024). "The deleterious effect of carbohydrates has been described in the carbohydrate-insulin model of obesity development, which postulates that the accumulation of adipose tissue is linked to the high secretion of insulin that occurs in response to the consumption of a high-carbohydrate diet." (PMID 38571752, 2024). "In addition, miR-122 was shown to be closely correlated with obesity, as were the levels of lipids, glucose and insulin in patients with a lower physical activity score; this effect correspondingly demonstrated a significant correlation with viral infection." (PMID 39030480, 2024).
Obesity (continued). "Additionally, its capacity to inhibit lipase activity and improve insulin sensitivity positions dragon fruit as a promising natural intervention for the management of obesity and related metabolic disorders." (PMID 39683835, 2024). "Furthermore, the results of a meta-analysis reported that resistant starch supplementation is associated with an improvement in blood glucose, insulinemia, insulin sensitivity, and resistance, especially in patients with diabetes and overweight or obesity." (PMID 38257161, 2024). "The adverse impact of sugar-rich beverages on the development of obesity may be attributed to their ability to induce rapid and substantial elevations in blood glucose and insulin levels." (PMID 38887258, 2024). "In the context of obesity, which is associated with a state of chronic, mild, low-grade inflammation and observed negative impact on GLUT-4 function, the body requires higher levels of insulin to facilitate glucose uptake into cells, including muscle cells." (PMID 38655176, 2024). "In this line, previous studies performed in our laboratory involving animal models of dietary obesity revealed a sexual dimorphism in insulin sensitivity and metabolic markers, with female rats exhibiting a better systemic insulin sensitivity profile compared to males." (PMID 39339665, 2024). "Obesity plays a major role in the development and progression of DM, leading to a reshaped metabolic microenvironment, reducing insulin signaling and increasing blood glucose levels due to excessive nutrient accumulation, inflammation, autophagy disruption, and energy imbalance." (PMID 39459430, 2024). "The odds of overweight/obesity increased by 7% for every one-unit increase in serum insulin." (PMID 38941300, 2024). "Several potential mechanisms might help to understand how obesity itself contributes the formation of kidney stones, even in individuals with metabolic health who are relatively sensitive to insulin." (PMID 39014388, 2024). "In addition to these, we noticed differences in the impairment of glucose homeostasis induced by obesity between LanCL1 Ctr and cKO mice, and the obese cKO mice had higher levels of blood glucose, insulin, and leptin than the obese Ctr mice." (PMID 38397850, 2024). "Obesity and excessive weight gain during pregnancy have been associated with increased risk of LGA children, probably through maternal and fetal dysregulation of glucose, insulin, lipid, and amino acid metabolism." (PMID 38698309, 2024). "It is likely that many of these patients fulfilled criteria for A−β+ KPD, given that they were overweight or had obesity at presentation and could discontinue insulin therapy with good glycemic control on metformin." (PMID 38765897, 2024). "This may be attributed to hormonal changes affecting insulin sensitivity during puberty, and the more severe obesity issues in adolescent patients also affect peripheral tissue insulin sensitivity." (PMID 38962677, 2024). "These HFD mice show increased obesity and insulin action impairment, much like db/db mice." (PMID 38541736, 2024). "Similarly, obesity-associated circulating miR-222, in addition to hepatocytes, can also reach muscle cells to downregulate IRS1 and insulin signaling, thereby contributing to insulin resistance and glucose intolerance in obesity." (PMID 39769251, 2024). "Obesity decreases insulin sensitivity, leading to a higher serum glucose level." (PMID 38999751, 2024). "Furthermore, the gut commensal Bacteroides acidifaciens reportedly prevents obesity and improves insulin sensitivity in mice, while Bacteroides have been shown to promote branched-chain amino acid catabolism in brown fat and inhibit obesity in mice." (PMID 38299011, 2024). "In summary, lycopene’s multifaceted role in combating obesity-related metabolic disorders is supported by its ability to reduce oxidative stress, inflammation, and lipid accumulation while improving glucose metabolism and insulin sensitivity." (PMID 39519540, 2024).
Obesity (continued). "Obviously, depending on the duration of feeding, different research groups have explored different perspectives in terms of how HFD contributes to the development of metabolic anomalies and obesity, including insulin resistance, intramuscular lipid droplet accumulation, and mitochondrial function." (PMID 38044359, 2024). "The prevalence of these pathologies, however, trails the rise of obesity with an average delay of 10–15 years as shown for diabetes, and the progressive damage from sustained hyperglycemia and impaired insulin action in the target tissues is suspected to be responsible for this observation." (PMID 38672413, 2024). "In conclusion, this study demonstrates that dapagliflozin alleviated HFD-induced reproductive dysfunction independently of obesity, peripheral tissue insulin resistance, and systemic inflammation, suggesting its potential as a promising treatment for diet-related ovulation disorders." (PMID 39906039, 2024). "However, obesity decreases serum adiponectin concentrations, with a consequent decrease in insulin sensitivity." (PMID 38473918, 2024). "Indeed, in HFD-fed mice, MSI-1436 significantly decreased obesity by reducing insulin levels, decreasing body weight, lowering lipid content, decreasing adipocyte size, and suppressing food intake." (PMID 39238503, 2024). "Additionally, in obesity, tissues are less sensitive to insulin, which begins to be produced in excess." (PMID 39795949, 2024). "One possible explanation could be a long-term impairment of pancreatic inputs from the brain, as occurs in states of obesity and hypothalamic insulin resistance, which disrupts the balance of inputs to the beta cell." (PMID 38363340, 2024). "It distributes in both human and mouse WAT, which is regulated by insulin and obesity." (PMID 39538244, 2024). "An early metabolic consequence of obesity is disruption of glucose and insulin homeostasis." (PMID 38917085, 2024). "A clinical study demonstrated altered endocannabinoid system activity in obesity and metabolic conditions, revealing significant differences in endocannabinoid levels between insulin-resistant obese postmenopausal women and their insulin-sensitive counterparts." (PMID 39433509, 2024). "Thus, obesity is closely related to reduced adiponectin levels, as it reduces insulin sensitivity and increases liver fat levels." (PMID 38612504, 2024). "Obesity and hypertension share common pathophysiological mechanisms, such as overactivity of the renin–angiotensin–aldosterone and the sympathetic nervous systems, insulin resistance, and disruption of the leptin pathway." (PMID 39457606, 2024). "The complex of these metabolic activities confirms the pleiotropic activity of FGF21, improving insulin sensitivity, hepatic steatosis, and body weight and leading to its recognition as a potential therapeutic target for obesity-related metabolic disorders, including NAFLD/MASLD." (PMID 39409124, 2024). "The old concept did not satisfactorily explain why hyperinsulinemia causes obesity in insulin-resistant fat cells, because hyperinsulinemia is essential for the accumulation of lipids within insulin-sensitive tissues." (PMID 39769002, 2024). "Additionally, the beneficial effects of menthol extend to improving insulin sensitivity and combating obesity, as evidenced in both in vitro and in vivo studies." (PMID 38732127, 2024). "Obesity triggers lipotoxicity, mitochondrial dysfunction, adipose tissue dysfunction, gut microbiome imbalance, low-grade inflammation, and, ultimately, reduces insulin sensitivity." (PMID 39335526, 2024). "Trends included a positive association of HS C-reactive Protein and insulin and obesity as well as a negative association between blood lead level and blood cadmium level and obesity." (PMID 38820332, 2024).
Obesity (continued). "However, obesity-related insulin resistance reduces the effect of insulin on lipolysis, altering lipid metabolism and leading to a several-fold increase in triglyceride and cholesterol levels late in pregnancy." (PMID 39690358, 2024). "Although little is known about the function of KRTCAP3, it affects obesity and insulin sensitivity." (PMID 38658550, 2024). "Additionally, anti-obesity agents targeted body weight reduction and fat accumulation, improving insulin sensitivity by modulating appetite and fat metabolism." (PMID 39737158, 2024). "Similarly, exposure to obesogens can change the expression of miRNAs that are important for lipid metabolism, insulin signalling, and adipocyte differentiation, all of which can lead to the development of obesity." (PMID 38790597, 2024). "Thus, insulin emerges as a crucial factor driving airway hyperresponsiveness in individuals with obesity." (PMID 39316677, 2024). "Furthermore, the beneficial effects of menthol extended to positive impacts on insulin sensitivity and obesity improvement, as clearly demonstrated in both in vitro and in vivo studies." (PMID 38732127, 2024). "Understanding the complex interplay between the host and the gut microbiota and its products can increase the understanding of the pathogenesis of obesity, insulin resistance and potentially point towards new treatment modalities for obesity and its complications." (PMID 38427692, 2024). "Collectively, our findings indicate that β-cell GHSR has a major impact on insulin secretion in aging but not obesity, and GHSR deficiency protects against STZ-induced β-cell injury in aging." (PMID 38794702, 2024). "The proposed hypotheses underlining excessive adiposity and gastrointestinal cancer risks include altered insulin and IGF-1 signaling, chronic low-grade inflammation associated with obesity, and disruptions in sex hormone metabolism." (PMID 39335195, 2024). "However, in obesity and T2D, the insulin signalling pathway is impaired, leading to insulin resistance in macrophages." (PMID 38988822, 2024). "When β-cells cannot adjust to the increased insulin demand imposed by factors that increase metabolic demand, such as glucocorticoids, pregnancy, or obesity fasting and/or fed hyperglycemia may occur." (PMID 39741884, 2024). "CRP followed the same pattern as obesity measures, with significant inverse correlations for 3/70 markers, whereas insulin levels at the end of the hyperinsulinemic-euglycemic phase displayed positive weak tendencies with inflammatory responses (Supplement S3)." (PMID 37400734, 2023). "The “accelerator hypothesis” or the wider “ꞵ-cell stress hypothesis” suggests that biological factors such as overweight and obesity trigger increased insulin demand leading to endoplasmic reticulum stress." (PMID 37919779, 2023). "Another study indicated that the presence of insulin in the olfactory bulb could be connected with the process of satiation and the pathogenesis of obesity." (PMID 38248819, 2023). "Our data suggest that the appearance of altered prandial insulin secretion reflected in OGTT is a better indicator of increased inflammasome activation and OS damage and therefore, of a higher risk of the development of obesity-related metabolic complications." (PMID 37599368, 2023). "However, when solely children with obesity were studied, VO2max relative to FFM was positively associated with insulin sensitivity." (PMID 37147377, 2023). "In particular, evidence from a low-protein maternal diet rat model shows that miR-483-3p upregulation is associated with inhibited adipocyte differentiation and maturation, leading to altered insulin sensitivity and triglyceride deposition, which are precursors of obesity in offspring." (PMID 37338777, 2023). "Compared to MICT, three to 4 months of HIIT exerted apparent effects on fasting insulin decreases, and cardiovascular fitness increases in males (mean age 42 years) and females (mean age 21.2 years) with obesity." (PMID 37608837, 2023).